NOX1 (NADPH oxidase 1)
Diseases named in the same sentence as NOX1 in open-access papers (continued):
Sharing a sentence is not in itself a finding about the gene and the disease.
tumor (continued). "At higher doses of CAP, the effect on control tumor cells (siCo) remained dependent on NOX1, but cells with the knockdown of NOX1 (siNOX1) and subsequent downmodulation of catalase, also showed apoptosis induction." (PMID 31578342, 2019). "In conclusion, we showed that blocking NOX1 with the novel small-molecule inhibitor GKT771 inhibits tumor growth in mice." (PMID 31249132, 2019). "Taken together, these results demonstrate that the effect of the NOX1 inhibitor GKT771 on decreasing tumor growth is, at least in part, dependent on IFN-γ." (PMID 31249132, 2019). "As NOX1 inhibition increased tumor infiltration by inflammatory macrophages, we tested the effect of GKT771 on TILs and tumor-associated natural killer T cells (NKT) cells, two cell types with potent antitumor activities." (PMID 31249132, 2019). "Blocking NOX1 with the novel small molecule inhibitor GKT771 inhibits tumor growth in mice by targeting tumor lymph/angiogenesis and promoting antitumor immune cells recruitment." (PMID 31249132, 2019). "In the HepG2 tumor cell line, Nox1 activity seems to be responsible for metabolic restructuring (concerning for instance the Warburg effect), and Nox1 is therefore considered to be pro-tumorigenic." (PMID 30084091, 2018). "VEGF mRNA was upregulated by NOX1 in tumours, and both VEGFR1 and VEGFR2 were highly induced in vascular cells of NOX1-expressing tumours." (PMID 30459931, 2018). "Nox1 upregulation enhances Wnt/β-catenin and Notch pathways and disrupts tumor progression by pro-apoptotic mechanisms." (PMID 29867954, 2018). "Analysis of expression levels of NOX1 in samples recovered 7 days after tumor cell injection showed, as expected, marginal silencing of the target gene, in contrast to the >80% reduction of NOX1 levels at time of injection." (PMID 29915721, 2018). "Using a xenograft model from tuberin-null tubular cells in nude mice, both anti-sense Nox4 and GKT137831, a specific inhibitor of Nox1/4, significantly inhibited the tumor growth." (PMID 29491408, 2018). "Depletion of NOX1 and NOX4 partially rescued the growth inhibition of PARP1-deficient tumor xenografts." (PMID 29684820, 2018). "It has been argued that because NOX1 expression can be enhanced by differentiating agents that decrease tumor cell proliferation, the function of NOX1-induced O2 ̇̄ production at the epithelial surface is to enhance host defense rather than mitogenesis." (PMID 28330872, 2017). "Increased NOX1 expression produced by IL-4 exposure in the DLD-1 line, similar to HT-29 cells, was also associated with an increase in tumor cell growth and the production of ROS." (PMID 28498822, 2017). "Increased expression of NOX1 also accompanies activating mutations in K-RAS, a proto-oncogene with a key role in growth autonomy of tumor cells." (PMID 28626501, 2017). "Global genetic ablation of Nox1 was shown to impair tumour angiogenesis in mice, while (again global) genetic deletion of Nox2 or Nox4 was reported to reduce blood flow recovery in ischemic mouse hindlimb models." (PMID 28433660, 2017). "Because stable NOX1 knockdown in HT-29 cells significantly decreases tumor cell proliferation, we examined the effect of IL-4 exposure on the growth of parental HT-29 cells and NOX1 knockdown clonal variants." (PMID 28498822, 2017). "To study the effect of NOX1 silencing on tumor growth in vivo, we established xenografts from parental HT-29 cells and the SC and 6A clonal lines in athymic mice." (PMID 28330872, 2017). "We identified several protein functions dysregulated in the presence of reduced NOX1 levels, providing interesting indications regarding the involvement of NOX1 in the regulation of tumor cell metabolism." (PMID 25806803, 2015). "Further protein functions dysregulated upon the depletion of NOX1 also support previous reports on the role of this enzyme in regulating tumor growth." (PMID 25806803, 2015).
tumor (continued). "From these observations, we conclude that NOX1 promotes tumor angiogenesis by inhibiting the anti-angiogenic factor PPARα." (PMID 21326871, 2011). "From these results, we conclude that NOX1 plays a critical role in promoting tumor angiogenesis and tumor progression." (PMID 21326871, 2011). "Based on these data, it is clear that NOX1 and derived ROS products impede the migration of vascular smooth muscle and tumor cells." (PMID 21326871, 2011). "Excessive ROS production by T15 treatment activates different counter mechanisms trying to partially protect the tumor cells against oxidative stress, such as the higher expression of NOX1 on MCF7 cells; PARK7, PRDX1 and PRDX3 on MDA-MB231 cells; and UCP1 elevation in PANC1 cells." (PMID 41011284, 2025). "Glutamine inhibits ferroptosis via the ALK5/NOX1 axis, promoting tumor growth." (PMID 41018102, 2025). "Within 26 tumor types, NOX1 was highly expressed in tumor compared to adjacent normal tissues." (PMID 37679792, 2023). "TMI-5 treatment had no additive effect in tumor-bearing NOX1-deficient mice as compared to the corresponding vehicle-treated mice." (PMID 38137406, 2023). "Moreover, in non-tumor hepatocyte, such as HepaRG cells, NOX1 and NOX4 are even lower (at least by an order of magnitude); however, in these, DUOX2 is readily detected." (PMID 37189460, 2023). "Interestingly, we demonstrated that targeting ADAM17 encompasses the NOX1-sMCAM pathway but offers additional anti-tumor effects that regulate TAM recruitment." (PMID 38137406, 2023). "Reduced tumor angiogenesis from GKT771 treatment was only observed in Nox1 sufficient mice, but not Nox1 deficient mice, suggesting that GKT771 inhibits tumor angiogenesis by targeting NOX1." (PMID 35741081, 2022). "Notably, NOX1 knockdown remarkably abolished the tumor-promoting role of LINC00674 in HCC cells (P<0.05)." (PMID 36118523, 2022). "Further, Nox1 is highly expressed in colon cancer and supports tumor growth." (PMID 35681445, 2022). "Thus, we suggested that LINC00674 activated the mTOR signaling pathway and facilitated tumor progression by enhancing NOX1 expression in HCC cells." (PMID 36118523, 2022). "Moreover, the staining of Ki-67 and NOX1 in tumor tissues obtained from the LINC00674 knockdown group was significantly weaker than the control group (P<0.05)." (PMID 36118523, 2022). "We also examined whether iodonium analogs, in addition to producing FAD adducts that interfere with electron transfer to oxygen across tumor cell membranes, might have other direct effects on NOX1 expression." (PMID 34829628, 2021). "Nox1-deficient, but not Nox4-deficient, animals showed strongly reduced tumor numbers and size and reduced liver damage." (PMID 33669824, 2021). "Investigation supports that low level 1O2 (derived from CAP or via interaction with long lived species of PAM) may interact with tumor cells surface carrying NOX1, SOD, and CAT." (PMID 33477494, 2021). "It seems appropriate that additional branches of signaling chemistry that were elucidated in this way might later be tested for relevance in other tumor cell systems that are also defined by the classical NOX1/catalase connection." (PMID 34679719, 2021). "It is also obvious that the hierarchy of interactions established for MKN-45 cells is specifically relevant for tumor cells and has no impact on nonmalignant cells, as these lack the key features of active NOX1 and membrane-associated catalase." (PMID 34679719, 2021). "Total ROS levels in tumor tissue, tumor cell proliferation and hepatic levels of the proinflammatory cytokines IL-6 and TNF were reduced after chemically induced liver damage in Nox1-deficient animals." (PMID 33669824, 2021). "One mechanism favoring tumor angiogenesis is the inhibition of PPARα by the NADPH oxidase NOX1." (PMID 32785018, 2020).
tumor (continued). "The expression level of NOX1 protein was assessed with our mAb using multi-tumor tissue microarrays containing normal, benign, and malignant tissue samples of various anatomical origins by immunohistochemical (IHC) staining to establish which malignancies are associated with NOX1 overexpression." (PMID 32428030, 2020). "Accordingly, NOX1/ROS signaling may contribute to the activation of EGFR signaling by suppressing PTP functions, which may be a major tumor-promoting mechanism of NOX1/ROS signaling." (PMID 30700829, 2019). "This explanation has been experimentally excluded through the quantitation of NOX1 inhibition and through experiments in which tumor cell apoptosis was initiated by NO-mediated catalase inhibition, in the absence of primary 1O2 and fully dependent on secondary 1O2." (PMID 31558835, 2019). "Due to the parallel expression of NOX1 in the membrane of tumor cells, the attack on catalase by primary 1O2 provokes secondary 1O2 generation, further catalase inactivation, intracellular glutathione depletion and intercellular RONS-mediated apoptosis signaling." (PMID 31578342, 2019). "Thus the role of primary 1O2 generated from long-lived species derived from CAP treatment seems to be restricted to a merely triggering function for the “biochemical switchboard” of the tumor cells that is composed of NOX1, catalase and SOD." (PMID 31578342, 2019). "NOX1 deficiency affects tumor angiogenesis but not developmental angiogenesis and macrophages in healthy organs." (PMID 31249132, 2019). "This suggests that VEGFR-2 and NOX1 promote tumor growth through different mechanisms of action." (PMID 31249132, 2019). "Sustained NOX1 activity and expression of membrane-associated catalase by tumor cells are the most remarkable redox-related differences between tumor cells and nonmalignant cells." (PMID 31578342, 2019). "Bauer and Graves16 and Bauer17,18 suggested that low concentrations of 1O2 from CAP, or derived through interaction of long-lived species in PAM, would interact with the surface of tumor cells, that carries NOX1, catalase and SOD, in the same way for extracellular 1O2 generated by a photosensitizer." (PMID 31578342, 2019). "If the conclusions drawn in this discussion are correct, the strong H2O2 generation after direct CAP treatment should be prevented a) by the singlet oxygen scavenger histidine during treatment, b) by inhibition of NOX1 of the tumor cells by AEBSF or c) through siRNA-based knockdown of NOX1." (PMID 31558835, 2019). "This suggests that NOX1 could play a key role in the initial phases of the angiogenic switch in the A549 LKB1mut tumor xenograft model." (PMID 29915721, 2018). "Thus, the NOX1 tumour-promoting effects were likely to be due to activation of pathways distinct from NOX2." (PMID 30459931, 2018). "Perturbing ROS homeostasis or inhibition of NOX1 reduced tumor growth and angiogenesis in vivo and could represent a new possible therapeutic approach in LKB1-deficient KRAS-mutated tumors." (PMID 29915721, 2018). "Finally, we show the efficacy of a Nox1/4-specific inhibitor in ameliorating the tumor growth in mice." (PMID 29491408, 2018). "This study disclosed for the first time an effect of LKB1 on NOX1 expression in tumor cells." (PMID 29915721, 2018). "Therefore, although LKB1 acted as suppressor of NOX1 expression in all cell lines analyzed, other endogenous factors are likely to modulate NOX1 expression in tumor cells." (PMID 29915721, 2018). "Furthermore, there was a significant relationship in both tumor samples and normal tissues between levels of IL-4Rα and NOX1 mRNA." (PMID 28498822, 2017). "Furthermore, NOX1-dependent ROS are actively involved in stimulating tumor cell proliferation that is related, in part, to an increase in cell cycle progression through S-phase." (PMID 28498822, 2017). "Nox1−/− mice also had reduced tumor volume and vasculature in a tumor growth assay model." (PMID 28587189, 2017).
tumor (continued). "The NOX enzymatic family members (NOX1-5, DUOX1-2), through isoform specific superoxide or hydrogen peroxide production, have been associated with tissue remodeling, resistance to apoptosis, tumor cell proliferation and metastasis, and enhanced angiogenesis." (PMID 28578276, 2017). "However, in a recent study in which the consequences of the ablation of Nox1,2 or 4 were assessed in a slow-growing mouse tumour model, only Nox4 was found to contribute positively to angiogenesis." (PMID 28433660, 2017). "Moreover, it has been recently reported that HNE induced apoptosis in a wide variety of tumor cells expressing NADPH oxidase 1 (NOX1), a ROS-producing enzyme, by inactivating their membrane-associated catalase." (PMID 31435505, 2017). "It has been proposed that increased ROS levels derived from elevated NOX1 expression may stimulate tumor initiation through activation of NF-κB signaling." (PMID 28578276, 2017). "In addition to increasing NOX1-dependent cell cycle progression, as reported in this study, IL-4 has been demonstrated to stimulate tumor cell proliferation by enhancing the expression of anti-apoptotic proteins and/or signaling through the MAPK pathway." (PMID 28498822, 2017). "We studied both cultured cells and tumor xenografts developed from those cells to determine whether growth conditions modulated the effect of NOX1 inhibition on gene expression." (PMID 28330872, 2017). "The NADPH oxidase subunit NOX1 has been related to tumor biology in several cancer entities." (PMID 25806803, 2015). "Utilization of two characteristic and specific ROS-related features of tumor cell, namely NOX1-dependent generation of extracellular superoxide anions and membrane-associated catalase, warrants strict selectivity of apoptosis induction with respect to the tumor phenotype." (PMID 26225731, 2015). "However, based on human tumor tissue array findings of diminished NOX1 expression at a more advanced tumor stage, it is suggested that tumor-promoting action of NOX1 seems to be an early event." (PMID 26116564, 2015). "Tumor cells have increased rates of protein synthesis and turnover and our results suggest that NOX1 might play a role in controlling these processes in hepatic tumor cells." (PMID 25806803, 2015). "Furthermore, the potential for GKT136901 to be used as a NOX1/4 specific inhibitor in prevention of tumor angiogenesis is also demonstrated." (PMID 21326871, 2011). "Similarly, Nox1 expression converts DU-145 prostate epithelial cells from weak to strong tumorigenic potential, with a corresponding increase in tumor vascularity, pointing out the generality of the angiogenic effect of Nox1." (PMID 24281073, 2010). "Understanding these mechanisms may provide insight into Nox1 and redox signaling components as potential therapeutic targets to inhibit tumor progression." (PMID 20661536, 2010). "Nox1 and its regulators NoxO1 and NoxA1 are expressed greater in human gastric and intestinal adenocarcinomas than in normal gastric mucosa, suggesting that Nox protein activation could be a sign of tumor transformation." (PMID 38742936, 2024). "Finally, sMCAM targeting blocks NOX1-dependent CRC tumor growth." (PMID 38137406, 2023). "However, the molecular mechanisms by which NOX1 targeting affects tumor growth, angiogenesis, and the TME immune and inflammatory cell components are largely unknown." (PMID 38137406, 2023). "Thus, NOX1 may contribute to remodeling lipid metabolism in tumor cells since HMG-CoA synthase catalyzes the second step of the mevalonate biosynthesis, leading to lipid, steroid (including cholesterol), and isoprenoid biosynthesis." (PMID 36768405, 2023). "However, anti-sMCAM mAb treatment did not further reduce tumor growth in NOX1-deficient mice as compared to WT mice." (PMID 38137406, 2023). "Notably, NOX1 knockdown remarkably abolished the tumor-promoting role of LINC00674 in HCC cells." (PMID 36118523, 2022).
tumor (continued). "Hence, alterations of NOX1 expression might occur as consequence of changes in epigenetic marks following vector-mediated re-expression of LKB1 in tumor cells." (PMID 29915721, 2018). "Therefore, in view of our findings, it is conceivable that some of the effects on VEGF expression that follow interventions on LKB1 might depend on modulation of NOX1 levels in tumor cells." (PMID 29915721, 2018). "Gene-neighbour and gene set enrichment analyses revealed that NOX1/2/5 were strongly correlated with genes associated with cancer cell survival and metastasis, whereas increased NOX4 and DUOX1 expression was associated with genes that inhibit tumour progression." (PMID 28894215, 2017). "Also Nox1 siRNA inhibited the effects of LPS on tumour cell adherence." (PMID 23071493, 2012). "Use of a dual NOX4/NOX1 inhibitor impaired CAF actions and reduced tumour growth in vitro and in two different in vivo iCCA experimental models." (PMID 40820091, 2025). "Accordingly, NOX4/NOX1 dual inhibition impairs CAF functions in vitro and reduces tumour burden in preclinical in vivo models of iCCA." (PMID 40820091, 2025). "Studies have shown that SHMT1 inhibits NADPH oxidase 1 in HCC, thereby reducing ROS levels, which in turn suppresses tumor cell invasion and metastasis, indicating that SHMT1 plays a critical role in maintaining metabolic homeostasis." (PMID 40738465, 2025). "Ferroptosis markers was closely related with clinical characteristics; ferroptosis score based on GPX4, NOX1, and FACL4 can effectively reflect CRC prognosis, tumor progression and ACT responsiveness with high C‐index." (PMID 35855531, 2023). "IDO1, NOX1, CXCL3, IL1RL2 and NOS2 were upregulated, as their expression levels were lower in the healthy group and higher in the tumor group." (PMID 36911403, 2023). "RT-qPCR and IHC indicated that the expression of GLS, NOX1, HOXC6, TNNT1 and PLA2G12B were up-regulated in tumor tissues, compared with those in normal tissues, and all of GLS, HOXC6, NOX1 and PLA2G12B were closely related with patient survival." (PMID 37333810, 2023). "Higher expression of GPX4, lower expression of NOX1 and FACL4 indicated larger primary tumor size (p = 0.001)." (PMID 35855531, 2023). "Based on GSEA and CIBERSORT analysis, tumor cells with low GPX4 tend to be infiltrated by higher proportion of CD4+ T cell, expression of NOX1 was negatively correlated with M1 macrophage infiltration and ACSL4 was positively close to CD8+ T cell infiltration." (PMID 35855531, 2023). "In particular, we dissect the contribute of NOX1, NOX2, and NOX4 enzymes in the modulation of cellular metabolism and highlight their potential role as a new therapeutic target for tumor metabolism rewiring." (PMID 36768405, 2023). "NOX1 activation, increased oxidant production and EGFR activation can lead to the upregulation of MMPs which can then promote tumor metastasis." (PMID 37516013, 2023). "In this work, we decided to determine the involvement of NOX1 and ADAM17 in the generation of sMCAM from blood vascular endothelial and cancer cells and to demonstrate its contribution to tumor angiogenesis and cancer progression." (PMID 38137406, 2023). "New findings of NOXs in physiologic and pathologic angiogenesis have dissected the roles of NOX1, NOX2, NOX4, and NOX5 in ocular vascular diseases, cardiovascular diseases, and tumor angiogenesis." (PMID 35741081, 2022). "The NOX family, which includes NOX1, NOX2, NOX3, NOX4, and NOX5 subtypes, is a key mediator of cyclic hypoxia-mediated ROS production and tumor progression." (PMID 36278207, 2022). "The impact of PPARγ on cancers is complex and bidirectional, PPARγ acts as a tumor promoter by induction of lipogenic gene ACLY, MIG12, FASN, and NR1F1, stem cell-related gene KLF4, ALDH and upregulation Nox1 ROS, and VEGF." (PMID 36587194, 2022).